ACTN4 (actinin alpha 4)
Diseases named in the same sentence as ACTN4 in open-access papers (continued):
Sharing a sentence is not in itself a finding about the gene and the disease.
focal segmental glomerulosclerosis (23 papers, 2004 to 2026). A renal disorder characterized by sclerotic lesions in the glomeruli. "ACTN4 is genetically associated with focal segmental glomerulosclerosis in OMIM, and it is included in a very recent kidney-disease gene panel towards a comprehensive genetic diagnosis of cystic and glomerular inherited kidney diseases." (PMID 32957963, 2020). "ACTN4 encodes α-actinin 4 (alpha-actinin-4), a cross-linking protein belonging to the spectrin superfamily and mutations in this gene cause focal segmental glomerulosclerosis in humans." (PMID 31597446, 2019). "Previous studies have been reported that mutations in ACTN4 cause focal segmental glomerulosclerosis." (PMID 27613243, 2016). "For example, a mutation in ACTN4, which encodes actinin 4, causes hereditary focal segmental glomerulosclerosis (FSGS)." (PMID 27227331, 2016). "Mutations in the Alpha-actinin-4 gene (ACTN4) cause a rare form of familial focal segmental glomerulosclerosis in humans." (PMID 26301083, 2015). "ACTN2 mutations have been linked to a range of cardiomyopathies, and ACTN4 mutations cause a kidney condition called focal segmental glomerulosclerosis." (PMID 26312134, 2015). "The importance of the actin cytoskeleton in glomerular and podocyte function is highlighted by mutations in α-actinin-4 (ACTN4), which leads to familial focal and segmental glomerulosclerosis (FSGS)." (PMID 19652713, 2009). "Furthermore, it was previously reported that mutation in ACTN4, which encodes α-actinin-4, causes focal segmental glomerulosclerosis and solidifies the actin network in podocytes." (PMID 33922367, 2021). "Importantly, mutations in the ACTN4 promoter that correlate with decreased expression have been identified in patients with the focal segmental glomerulosclerosis." (PMID 31766144, 2019). "Mutations of ACTN4 cause an autosomal dominant form of focal segmental glomerulosclerosis (FSGS)." (PMID 29043128, 2015). "Secondly, human studies have identified five dominant ACTN4 mutations that cause the kidney disease focal segmental glomerulosclerosis (FSGS), while actinin-4 knockout mice exhibit altered podocyte morphology, develop glomerular disease, and finally, experience kidney failure." (PMID 26312134, 2015). "In humans, ACTN4 mutations cause a form of focal segmental glomerulosclerosis (FSGS)." (PMID 15208719, 2004). "Genetic mutations in alpha-actinin 4 (ACTN4) are one cause of familial focal segmental glomerulosclerosis (FSGS) and steroid-resistant nephrotic syndrome (SRNS) in early adulthood, eventually progressing to end-stage kidney disease." (PMID 41013435, 2025). "Our suspicion was that nephropathy was likely due to secondary focal segmental glomerulosclerosis (FSGS) because both WT1 and ACTN4 mutations are more commonly associated with FSGS than diffuse mesangial sclerosis (DMS)." (PMID 40890712, 2025). "Mutations or dysfunction in ACTN4 have been associated with kidney disorders like focal segmental glomerulosclerosis (FSGS), as well as metastatic cancers." (PMID 41156344, 2025). "Naturally-occurring mutations such as K255E, T259I and S262P ACTN4 cause focal segmental glomerulosclerosis (FSGS) in affected humans because of their elevated actin binding activities." (PMID 31664084, 2019). "Mutations in the actin-binding domain of ACTN4 cause an autosomal dominant form of focal segmental glomerulosclerosis (FSGS)." (PMID 27977723, 2016). "The crosslinker α-actinin-4 (ACTN4) forms catch bonds with actin filaments (F-actin) to support the function of kidney podocytes, and its force-insensitive K255E variant causes autosomal dominant focal segmental glomerulosclerosis (FSGS)." (PMID 41867833, 2026). "ACTN4 is closely associated with CKD, especially focal segmental glomerulosclerosis (FSGS)." (PMID 32957963, 2020).
cervical cancer (17 papers, 2014 to 2023). A primary or metastatic malignant neoplasm involving the cervix. "The present study was aimed at determining the serum levels of actinin-4 (ACTN4) in cervical cancer (CC) and investigating the diagnostic and prognostic value of serum ACTN4 in CC." (PMID 32855746, 2020). "A negative association between NHERF1 expression and levels of ACTN4 and β-catenin was found in mouse xenograft model and cervical cancer specimens." (PMID 29867145, 2018). "Higher carcinogenesis and development of cervical cancer are linked to increased ACTN4 expression." (PMID 35645371, 2022). "For example, HPV-16 E6 oncoprotein, following a decrease in Na + /H + exchanger regulatory factor 1 (NHERF1), increases ACTN4 actin cytoskeletal protein level and subsequently enhances actin polymerization, migration, and invasion of cervical cancer cells." (PMID 36681850, 2023). "Some of the most promising cervicovaginal fluid-based biomarkers for cervical cancer found until now are ACTN4, VTN, ANXA1, ANXA2, CAP1, and MUC5B." (PMID 35645371, 2022). "ACTN4, or alpha-actinin-4, is a promising biomarker candidate in cervicovaginal fluid for detecting cervical cancer in its precancerous stage." (PMID 35645371, 2022). "In recent years, accumulating evidence has shown that ACTN4 enhances migration and lymph node metastasis in colorectal cancer and promotes epithelial-to-mesenchymal transition and carcinogenesis of cervical cancer." (PMID 34380780, 2021). "Recent studies have reported that Na+/H+ exchanger regulatory factor 1 (NHERF1) is associated with cell proliferation through the Wnt/β-catenin signaling and negatively regulates ACTN4 expression in cervical cancer." (PMID 33363146, 2020). "Our previous study suggests that ACTN4 is involved in Akt-mediated β-catenin transcriptional activation in cervical cancer." (PMID 33363146, 2020). "In accordance with this finding, NHERF1 knockdown augmented the ACTN4 protein level in cervical cancer cells." (PMID 31766144, 2019). "Taken together, these data suggest that NHERF1 inhibits cervical cancer cells proliferation through reduction of β-catenin levels by regulation of ACTN4 expression." (PMID 29867145, 2018). "NHERF1 was further demonstrated to retard cell proliferation with the attenuation of Wnt/β-catenin pathway activation of cervical cancer cells in vivo and in vitro through suppression of α-actinin-4 (ACTN4) expression level." (PMID 29867145, 2018). "It was further demonstrated in cellular study that NHERF1 inhibition of cervical cancer cell proliferation through Wnt/β-catenin signaling was dependent on α-actinin-4 (ACTN4) expression." (PMID 29867145, 2018). "In the present study, we further revealed that NHERF1 inhibition of cervical cancer cell proliferation was mediated via ACTN4." (PMID 29867145, 2018). "Study from other groups showed that upregulation of ACTN4 enhanced proliferation of cervical cancer cells in cellullar and xenograft models by promoting stability of β-catenin through phosphorylation of Akt and GSK3β26,36." (PMID 29867145, 2018). "Suppression of NHERF1 in cervical cancer xenograft tumor increased its ACTN4 and β-catenin protein levels, and enhanced the levels of Ki67 by immunohistochemical staining." (PMID 29867145, 2018). "Taken together, these data indicate that NHERF1 inhibits cervical cancer cell proliferation via suppression of ACTN4 expression." (PMID 29867145, 2018). "In summary, the present study provides novel evidences for a tumor-suppressive role of NHERF1 in cervical cancer cell proliferation by attenuation of Wnt/β-catenin signaling via a decrease in ACTN4 expression." (PMID 29867145, 2018). "Our findings indicate that alpha-actinin-4 (ACTN4) is a promising candidate biomarker for the precancerous state of cervical cancer and that this CVF protein is very well suited for the development of a self-diagnosis test." (PMID 25215525, 2014).
cervical cancer (continued). "In addition, ACTN4 promotes metastasis to lSymph nodes in colorectal cancer as well as induces epithelial mesenchymal transition and tumorigenesis in cervical cancer, and it can be inferred that OTUD3 is also involved in these processes by regulating ACTN4." (PMID 37829187, 2023). "Although ACTN4 is involved in tumorigenesis and the epithelial–mesenchymal transition of cervical cancer, the role of ACTN4 in PCa remains unknown." (PMID 33363146, 2020). "Furthermore, the authors have shown that NHERF1 inhibits ACTN4-mediated stabilization of β-catenin, activation Wnt/β-catenin signaling, and hence suppresses the proliferation of cervical cancer cells." (PMID 31766144, 2019). "All these findings suggest that NHERF1 may suppress Wnt/β-catenin signaling activation via a decrease in ACTN4 levels to elicit anti-proliferation and tumor-suppressive effects in cervical cancer." (PMID 29867145, 2018). "ACTN4 may, therefore, play an important role in the development of a simple bedside assay for cervical cancer based on CVF components." (PMID 29143101, 2018). "In addition, ACTN4 is involved in cell movement and proliferation of cervical cancer cells." (PMID 32670437, 2020). "Hence, the authors hypothesized that ACTN4 regulated EMT in cervical cancer cells by activating Akt signaling pathway whereas the augmentation of their proliferation was achieved by stabilization of the β-catenin protein." (PMID 31766144, 2019). "Thus, it is highly possible that NHERF1 may inhibit proliferation of cervical cancer cells through regulation of ACTN4 protein expression." (PMID 29867145, 2018). "However, in addition to the virus titer, we also expected the genotype and time of infection to influence the ACTN4 expression because different virus types have different carcinogenic capacities and cervical cancer usually develops after a persistent HR-HPV infection." (PMID 25215525, 2014). "We have previously reported that ACTN4 induces the phosphorylation of Akt and GSK-3β in cervical cancer." (PMID 33363146, 2020). "We have previously reported that ACTN4 maintains β-catenin stability by Akt activation to promote EMT and tumorigenesis in cervical cancer." (PMID 33363146, 2020). "ACTN4 over-expression in Madin-Darby Canine Kidney (MDCK) cells and several cervical cancer cell lines resulted in EMT-like changes, which included increased motility and invasiveness." (PMID 31766144, 2019). "Downregulation of NHERF1 protein then leads to oncogenenic proliferation upon upregulation of ACTN4 and activation of Wnt/β-catenin signaling in HPV-active cervical cancer." (PMID 29867145, 2018). "ACTN4 was found to promote EMT and tumorigenesis by regulating Snail expression and the Akt pathway in cervical cancer." (PMID 29197410, 2017). "Furthermore, studies from other groups have shown that the ACTN4-Akt axis promotes the degradation of GSK-3β, leading to the stabilization of β-catenin and enhancement of migration and invasion of cervical cancer cells." (PMID 33628783, 2021). "ACTN4 induces the EMT and promotes cell migration and invasion in cervical cancer." (PMID 33363146, 2020). "However, when ACTN4 expression was knocked down by siRNA, NHERF1 had less effect on the cervical cancer cell proliferation." (PMID 29867145, 2018). "A high level of ACTN4 may therefore be an indication of a persistent oncogenic HPV infection and an increased chance of developing cervical cancer." (PMID 25215525, 2014). "Assuming that precancerous tissue is (partially) attacked by the immune system, we hypothesized that ACTN4 is released in the CVF from lysed epithelial cells with many other intracellular factors, including those involved in the development of precancerous lesions and/or cervical cancer." (PMID 29143101, 2018). "Upon depletion of ACTN4 expression, NHERF1 failed to inhibit the clonogenic capacity of cervical cancer cells." (PMID 29867145, 2018).
pancreatic cancer (17 papers, 2014 to 2024). "ACTN4 shows strong positivity (>75%) in pancreatic cancer, lung cancer, and renal cancer and moderate positivity (75–25%) in glioma." (PMID 39329952, 2024). "ACTN-4 has been reported to show increased protein expression in several types of cancers, such as colorectal cancer, pancreatic cancer, ovarian cancer, oral squamous cell carcinoma, salivary gland carcinoma, and lung cancer." (PMID 36139525, 2022). "In pancreatic cancer cells, siRNA knockdown of ACTN4 reduced the invasive potential of cancer cells." (PMID 36139525, 2022). "ACTN4 has been reported as a tumor promoter in gastric cancer, colorectal cancer and pancreatic cancer." (PMID 34998421, 2022). "Recurrent amplification of chromosome 19q13.1-2 has been reported in pancreatic cancer, in which ACTN4 is one of the candidate oncogenes." (PMID 33171868, 2020). "Patients with high expression of ACTN4 in pancreatic cancer have a worse prognosis after treatment with chemotherapy and radiation." (PMID 32670437, 2020). "In pancreatic cancer the expression of ACTN4 was increased in 63.0% of the cases and was accompanied by poor outcome." (PMID 33171868, 2020). "Experiments in colon and pancreatic cancer cells have shown that ACTN4 overexpressing cells are highly mobile and have a significantly increased metastatic ability." (PMID 29143101, 2018). "The ACTN4 expression was found in Langerhans islets at the mRNA and protein level; another study reported this protein as being secreted by pancreatic cancer stem cells." (PMID 30627566, 2018). "WAVE2 promoted pancreatic cancer cell motility and invasion by forming a complex with the actin cytoskeletal protein alpha‐actinin 4 (ACTN4)." (PMID 30353690, 2018). "ACTN4 amplification is frequently observed in patients with carcinomas of the pancreas, ovary, lung, and salivary gland, and patients with ACTN4 amplifications have worse outcomes than patients without amplification." (PMID 26288717, 2015). "When actinin-4 is reduced in the pancreatic cancer cell line, BxPC3-KD-ACTN4, with ACTN4 siRNA, the invasive ability in the invasion assay is decreased." (PMID 26288717, 2015). "ACTN4 gene amplifications were shown to correlate with pancreatic cancer and could be a potential biomarker for metastatic potency and for predicting the effectiveness of chemoradiotherapy in locally advanced pancreatic cancer." (PMID 29143101, 2018). "Moreover, our previous data demonstrated that some patients who strongly overexpressed the ACTN4 protein also had significant gene amplification of ACTN4, including patients with lung adenocarcinoma, salivary gland carcinoma, pancreatic cancer, and ovarian cancer." (PMID 27121206, 2016). "MINDY Lysine 48 Deubiquitinase 2 (MINDY2) interacts with and deubiquitinates ACTN4, stabilizes ACTN4, and activates the PI3K/AKT/mTOR signaling pathway to promote pancreatic cancer proliferation and metastasis." (PMID 39115875, 2024). "These proteins promote cell invasion by influencing ERK1/2 and Glycogen Synthase Kinase 3α/β (GSK-3α/β) signaling; Src, ERK1/2, and AMP-activated protein kinase 1 (AMPK1) signaling; and alpha-actinin 4 (ACTN4) and p27 signaling in pancreatic cancer, respectively." (PMID 31080558, 2019). "Transplantation of pancreatic cancer cells with siRNA-mediated reduction of ACTN4 expression into the pancreas of mice revealed no destructive invasion into the pancreas compared with control cells." (PMID 26288717, 2015). "We previously reported that coamplification of AKT2 and ACTN4 did not necessarily accord for invasion of pancreatic cancer 5,11." (PMID 24574362, 2014).
lung carcinoma (16 papers, 2014 to 2024). "Our current data are consistent with many previous studies, including a microarray and immunostaining data on ACTN4 and its association with pathways contributing to lung cancer metastasis." (PMID 25885339, 2015). "In addition, the ACTN4 levels are markedly associated with the poor prognosis of lung cancer, thyroid cancer, and salivary gland carcinoma." (PMID 32855746, 2020). "ACTN4 mutation causes the suppression of tumor cell growth and migration in lung carcinoma." (PMID 33363146, 2020). "Hence, exploring whether the effect of PHF23 on ACTN4 protein stability is implicated in the resistance process to EGFR-TKIs could provide a new target for combating drug resistance in lung cancer." (PMID 37626047, 2023). "Then, we experimentally verified that PHF23 activates the ERK signaling pathway by stabilizing ACTN4, thereby promoting proliferation, migration, and chemoresistance of lung cancer cells in vitro and in vivo." (PMID 37626047, 2023). "Consistently, our experiments suggested that the knockdown of ACTN4 partially abrogates the role of PHF23 in promoting chemoresistance in lung cancer." (PMID 37626047, 2023). "We confirmed that the downregulation of p-ERK was mediated by siACTN4 in two lung cancer cell lines, further supporting the role of ACTN4 in ERK signaling regulation." (PMID 37626047, 2023). "We decided to test the involvement of ACTN4 in the response of lung cancer cells to DNA damaging drugs with different mechanisms of action." (PMID 36476259, 2022). "In various cancers, including lung cancer, increased protein expression of ACTN4 indicates malignancy and metastatic potential." (PMID 36139525, 2022). "A549 showed the highest expression of the ACTN4 protein compared to the other lung cancer cell lines tested." (PMID 27121206, 2016). "Our results demonstrated that these functions of ACTN4 contribute to the process of lung cancer metastasis to the brain." (PMID 25885339, 2015). "The data confirmed the RNA-Seq results and showed the significantly increased expression of ACTN4 in the brain tumor tissues but comparable levels between primary lung cancer and the adjacent benign lung tissues of 10 cases of independent samples." (PMID 25885339, 2015). "ACTN4 contributes to the brain metastasis of lung cancer mainly through regulating actin cytoskeleton organization, cell motility, and focal adhesion." (PMID 25885339, 2015). "Our study provided the first RNA-Seq data to support the essential function of the ACTN4 gene and the relevant cytoskeleton organization pathways in the brain metastasis of lung carcinoma." (PMID 25885339, 2015). "In fact, gene amplification of ACTN4 has been detected in tumors from patients with pancreatic 11, ovarian 6,7, and lung cancers 13, and correlations between protein expression and gene amplification have been statistically recognized in some cancers." (PMID 24574362, 2014). "However, some researchers have found that P65 inhibits the proliferation of the lung cancer cell line H1299, and that overexpression of ACTN4 enhances this inhibitory effect." (PMID 30879239, 2020). "Based on this hypothesis, we examined whether expression of ACTN4 could be used to evaluate the metastatic potential of lung cancer cell lines in an in vitro assay." (PMID 27121206, 2016). "The contribution of ACTN4 to the process of lung cancer metastasis to the brain could be mainly through regulation of actin cytoskeleton reorganization, cell motility, and focal adhesion." (PMID 25885339, 2015). "Among these significant genes and pathways, ACTN4, encoding a nonmuscle actin cytoskeleton protein, and the pathway involved in regulation of actin cytoskeleton appeared to play a pivotal role in the process of lung cancer metastasis to the brain." (PMID 25885339, 2015).